EGFR (epidermal growth factor receptor)
Diseases named in the same sentence as EGFR in open-access papers (continued):
Sharing a sentence is not in itself a finding about the gene and the disease.
lung adenocarcinoma (continued). "Moreover, SCLC may also transdifferentiate from lung adenocarcinoma (LUAD) following loss-of-driver mutations such as epidermal growth factor receptor (EGFR)." (PMID 38395864, 2024). "However, the underlying reason for the favorable prognosis in PD-L1-positive cases in comparison to PD-L1-negative cases in EGFR-mutated lung adenocarcinoma remains unclear." (PMID 39281386, 2024). "Therefore, the PD-L1 expression status may serve as an indicator of the strength of its downstream signaling in EGFR-mutated lung adenocarcinoma, resulting in a higher malignant potential." (PMID 39281386, 2024). "However, after 9.6 months of oral ocitinib treatment, patients with advanced lung adenocarcinoma and EGFR T790M-positive mutations invariably exhibit acquired resistance to ocitinib, which results in disease progression and impacts the clinical prognosis of patients." (PMID 38957318, 2024). "Moreover, SCLC may also transdifferentiate from lung adenocarcinoma following loss-of-driver mutations such as epidermal growth factor receptor (EGFR)." (PMID 39723215, 2024). "Additionally, lung adenocarcinomas with calcification may be associated with ROS1 fusions as well as EGFR mutations and ALK fusions." (PMID 39391406, 2024). "Additionally, inhibition of mutant EGFR with the third-generation inhibitor osimertinib in lung adenocarcinoma cells has been shown by one group to cause the up-regulation of the tyrosine kinase receptor AXL, and by another group to cause the up-regulation of the mitotic protein kinase AURKA." (PMID 38473364, 2024). "This study showed that these inflammatory indices might have an important prognostic potential for advanced lung adenocarcinoma patients with EGFR mutations, receiving thoracic radiotherapy and might provide a basis for the individualized treatment of these patients." (PMID 36070068, 2023). "Therefore, mining peritumoral radiomic features may identify new biological markers for the non-invasive prediction of EGFR mutation in lung adenocarcinoma." (PMID 37749461, 2023). "This study aims to construct radiomics models based on [18F]FDG PET/CT using multiple machine learning methods to predict the EGFR mutation status of lung adenocarcinoma and evaluate whether incorporating clinical parameters can improve the performance of radiomics models." (PMID 37014500, 2023). "Our study verified the feasibility and potential superiority of multi-center 18F-FDG PET/CT-derived radiomics to identify EGFR mutation status and predict prognosis in lung adenocarcinoma, which may help to develop a non-invasive tool as a complementary to PET/CT for clinic." (PMID 37223682, 2023). "However, there is limited research on the efficacy of osimertinib in treating patients with advanced EGFR-mutated lung adenocarcinoma with bone metastases, and its efficacy and safety remain unclear." (PMID 37653755, 2023). "Furthermore, EGFR-resistant lung adenocarcinoma with RB1 mutations could transform into a more aggressive small-cell lung cancer." (PMID 37020866, 2023). "In conclusion, our preliminary findings in a small patient population indicated that FDG PET texture indices may be potential imaging biomarkers for the EGFR mutation status in patients with newly diagnosed lung adenocarcinoma, although the mechanism and biological significance remain unclear." (PMID 37185611, 2023). "Therefore, LUSC and lung adenocarcinoma should be discussed separately in terms of adjuvant clinical implementations, and patients with driver gene mutations, including EGFR sensitive mutations or ALK fusions, were excluded from the present study in order to eliminate the systematic bias." (PMID 37188197, 2023). "Hence, oncogenic CTNNB1 mutations may be found in about 6% of lung adenocarcinomas and may predict post-operative recurrence in EGFR-mutant LUADs." (PMID 37347751, 2023). "Therefore, our results may suggest that tumor heterogeneity is associated with EGFR mutation status in lung adenocarcinoma." (PMID 37749461, 2023).
lung adenocarcinoma (continued). "ERBB2 exon 20 insertions were reported as analogous to EGFR exon 20 insertions and associated with primary resistance to currently approved tyrosine kinase inhibitors because of steric hindrance in the drug-binding pocket and a poor response to immunotherapies in lung adenocarcinoma _ENREF_24." (PMID 35911441, 2022). "However, our study retrospectively obtained more comprehensive data of the tumors in 3D from CT images and was the first to further explore the relationship between EGFR mutation-related features and the response of EGFR TKI therapy in advanced lung adenocarcinoma." (PMID 36052262, 2022). "In addition to the genetic variant itself, the EGFR genotypes could show different effects on the clinicopathologic characters of lung adenocarcinoma when combining it with other genetic polymorphisms." (PMID 36011604, 2022). "Such a discrepancy may indicate that the proportion of ALK amplification, as an oncogene driver, is higher than that of an EGFR mutation, or that the application of alectinib is more effective than EGFR-TKIs in the treatment of co-mutated lung adenocarcinoma patients." (PMID 36107507, 2022). "Interestingly, the events are characteristic of EGFR mutation-positive lung adenocarcinomas." (PMID 35710642, 2022). "Therefore, this study aimed to explore the prognostic power of the combination of systemic inflammation markers and tumor glycolytic heterogeneity for the risk stratification of patients with advanced EGFR-mutated lung adenocarcinoma treated with a first-line TKI." (PMID 35053473, 2022). "However, results such as those in EGFR-mutated lung adenocarcinoma gives hope that in an appropriately selected patient population, metformin could improve outcomes." (PMID 36591457, 2022). "In addition, co-mutations of EGFR mutation lung adenocarcinoma patients may also influence the response to TKI treatment." (PMID 36528578, 2022). "EGFR mutation type(s) in CSF were largely concordant with those in the primary tumor (73.5% concordance for Huang and 90.9% concordance for Fan), proving that EGFR mutation testing in CSF from lung adenocarcinoma patients with CNS metastases is clinically feasible for guiding precision medicine." (PMID 36457515, 2022). "Given the high rate of EGFR mutations in Chinese lung adenocarcinoma patients, a previous study has demonstrated that exon 19 and 21 mutations combined with clinicopathological features could be a molecular marker to assess the efficacy of TKI treatment for NSCLC." (PMID 36230590, 2022). "Furthermore, in the subgroup of lung adenocarcinoma patients with the EGFR-L858R mutation, both WWOX rs3764340 C/G (OR = 5.209, p = 0.023) and rs73569323 C/T polymorphisms (OR = 3.886, p = 0.039) exhibited significant associations with the size of primary tumors and the invasion of adjacent tissues." (PMID 34948746, 2021). "However, whether these WWOX polymorphisms are related to the clinical risk of epidermal growth factor receptor (EGFR)-mutated lung adenocarcinoma is worthy of investigation." (PMID 34948746, 2021). "Additionally, the high rate of EGFR mutation and the use of the most recent anticancer therapeutics for lung adenocarcinoma may have considerably prolonged patient survival after recurrence." (PMID 33231358, 2021). "Our findings offer novel evidence that EGFR-mutant tumors have a higher infiltration of Tregs compared with wild-type tumors, which could be the main cause of impaired response to PD-1 pathway blockade in EGFR-driven lung adenocarcinoma." (PMID 34484468, 2021). "Although it is unclear whether an increase of miR‐1 is a cause or result of EGFR‐TKI resistance acquirement, we can consider that these results support the results of miRNA array analyses, and that an increase of miR‐1 is associated with EGFR‐TKI resistance in lung adenocarcinoma." (PMID 33305905, 2021).
lung adenocarcinoma (continued). "Furthermore, PHLPP levels may influence the initial response to TKIs, as low as PHLPP in pre-treatment specimens is strongly associated with reduced PFS for patients with EGFR-mutant lung adenocarcinomas treated with EGFR TKI." (PMID 34168988, 2021). "Therefore, we would like to argue that these data warrant a more sophisticated validation to establish a direct link between chemokine expression and Treg infiltration in the context of lung adenocarcinomas, for instance, by employing well-controlled EGFR-mutated genetically engineered mouse models." (PMID 35052732, 2021). "Moreover, EGFR-mutated (EGFR+) lung adenocarcinoma is more heterogeneous than EGFR− in CT images." (PMID 34307127, 2021). "As several randomized trials have extensively demonstrated, the presence of a classic sensitizing EGFR mutation is the most powerful predictive biomarker of response to monotherapy with first-generation TKIs and, thus, the most important prognostic factor in cases of advanced lung adenocarcinoma." (PMID 33435440, 2021). "Very recently, a genome-wide DNA methylation analysis revealed that HOXB9 DNA methylation was linked to intrinsic EGFR-TKI resistance and complementary to mutation profiling could discern whether lung adenocarcinoma patients would benefit from EGFR-TKI treatment." (PMID 34885084, 2021). "Thus, all lung adenocarcinoma cases in Malaysia should be tested for EGFR gene mutations." (PMID 34181354, 2021). "Furthermore, EGFR-mutated lung adenocarcinoma with concurrent mutations was more likely to recur." (PMID 34298845, 2021). "Moreover, the AUC in the receiver operating characteristic curve was greater than 0.75, which further suggested that the exosome miR-3913-5p expression level was associated with advanced progression of lung adenocarcinoma in patients with EGFR mutations during TKI use." (PMID 34391435, 2021). "Moreover, it is necessary to study whether these polymorphic changes alter the function of WWOX protein in EGFR-mutated lung adenocarcinoma patients, especially L858R-mutated lung adenocarcinoma patients." (PMID 34948746, 2021). "Therefore, whether these WWOX polymorphisms are related to the clinical risk of EGFR-mutated lung adenocarcinoma is worthy of investigation." (PMID 34948746, 2021). "For example, the genotyping of 3026 lung adenocarcinoma samples revealed a higher frequency of EGFR mutations in never smokers (42.5%) and former smokers (13.5%) compared to current smokers (4.9%); the most common EGFR mutations in this study included exon 19 deletions and L858R point mutations." (PMID 34202748, 2021). "Additionally, results from the drug-resistant cells suggest that CDK9 inhibitors, alone or in combination with sublethal doses of BRD4 inhibitor, would be efficacious for patients who are burdened with K-Ras or EGFR mutated lung adenocarcinomas and those who have developed therapy resistance." (PMID 34359807, 2021). "Consequently, tyrosine kinase inhibitors targeting epidermal growth factor receptor (EGFR) and anaplastic lymphoma kinase (ALK) have become the standard treatment for patients with metastatic EGFR‐ or ALK‐mutated lung adenocarcinoma, and these tests are performed in routine practice." (PMID 33960703, 2021). "In addition, a recent study of 19 lung adenocarcinoma patients found high frequencies of Treg infiltration despite low CD8 T-cells in EGFR-mutated lung adenocarcinomas, additionally suggesting that EGFR expression may affect Treg expansion within the TME." (PMID 35052732, 2021). "Therefore, it is important to further analyze whether additional genetic variants are synergistically involved in these lung adenocarcinoma patients with EGFR mutations." (PMID 34948746, 2021). "Therefore, the CD44 rs713330 polymorphism may be associated with the primary tumor size and invasion of lung adenocarcinoma in male patients, particularly those with wild-type EGFR." (PMID 32344833, 2020).
lung adenocarcinoma (continued). "Therefore, we may reasonably consider that MPLA tumours with EGFR mutations have imaging patterns similar to those of single lung adenocarcinomas, which emphasizes the need to apply CT features to predict EGFR mutation in MPLA lesions that cannot be biopsied." (PMID 32690092, 2020). "To determine whether the SOS1 inhibitor BAY-293 could generally synergize with EGFR-TKIs in EGFR-mutated lung adenocarcinoma cells, we extended our assessment of drug-drug synergy to isobologram analysis and Bliss independence analysis in six different EGFR-mutated lung adenocarcinoma cell lines." (PMID 32897190, 2020). "EGFR-tyrosine kinase inhibitors (TKIs), including gefitinib, erlotinib, and afatinib, have shown promising efficacy (60–80% response rate and 9–13 months of progression-free survival) in treating advanced lung adenocarcinoma harboring L858R or exon 19 deletion mutations in clinical trials." (PMID 32092879, 2020). "The hypothesis is that skin sample studies from EGFR‐mutated lung adenocarcinoma patients allow us to establish a relationship between EGFR expression or its signaling pathway derivatives, and gefitinib treatment response, potentially acting as a tool to avoid tumor biopsy related risks." (PMID 33015988, 2020). "Data for 57 patients with advanced EGFR-mutated lung adenocarcinoma who received afatinib combined with bevacizumab as first-line therapy at the Chang Gung Memorial Hospitals in Linkou and Kaohsiung and Taipei Tzu Chi Hospital from May 2015 to July 2019 were analyzed." (PMID 33113888, 2020). "Based on our findings, in advanced lung adenocarcinoma patients having insufficient tissue samples for EGFR mutation testing, liquid biopsy to determine EGFR mutation status might be particularly useful if they have lymph node involvement and/or bone metastasis." (PMID 31652678, 2019). "Collectively, these findings suggest that beyond the simple clinical correlation, TTF-1 might play an important role in EGFR-driven lung adenocarcinoma oncogenesis and it might be a biomarker of EGFR oncogenic addiction among patients with EGFR mutation-positive lung adenocarcinoma." (PMID 31196060, 2019). "Lung adenocarcinoma-associated mutations in exons encoding the tyrosine kinase domain of this receptor most commonly include either deletion of a four amino acid motif (LREA) in Exon 19 of EGFR or a point mutation in Exon 21, which substitutes Arginine for Leucine at position 858 (L858R)." (PMID 31291990, 2019). "Therefore, in this study, EGFR mutation status was detected in tumor tissues, as well as cell blocks and exosomes in MPEs of lung adenocarcinoma patients, in order to explore whether exosome could be an ideal source of tumor DNA for EGFR mutation detection." (PMID 31608233, 2019). "Interestingly, protein SUMOylation and hepatocyte growth factor could respectively reduce the effect of small molecule inhibitors on tyrosine kinase activity of mutated epidermal growth factor receptor of lung adenocarcinomas (LADC)." (PMID 29855336, 2018). "Also intriguingly, whether the MDSC is also linked to resistance to EGFR-TKIs in EGFR mutated lung adenocarcinoma." (PMID 29484139, 2018). "We hypothesize that carcinogens released by WSE produce frameshift truncations, resulting in loss of protein function in the tumor suppressors ATM and SMARCB1, and subsequent mutations in the oncogenes RET, KDR and EGFR exon 7 among others involved in the development of lung adenocarcinoma." (PMID 30093964, 2018). "Hence, the prognostic role of EGFR mutations in T1 lung adenocarcinoma is probably well-defined." (PMID 29849818, 2018). "The present study, therefore, hypothesizes that various activities of EGFR pathways associated with EGFR mutation and EGFR-TKI resistance could possibly change the expression levels of MMP-1 in EGFR-TKI–resistant lung adenocarcinoma and contribute to the development of EGFR-TKI resistance." (PMID 29463039, 2018).
lung adenocarcinoma (continued). "Therefore, we investigated whether there is a distinctive mutation pattern in the subtypes of lung adenocarcinoma responsive to EGFR-TKI." (PMID 30522449, 2018). "There were 85 patients who were diagnosed as advanced lung adenocarcinoma with epidermal growth factor receptor (EGFR) 19 or 21 exon mutation in thoracic surgery of Xuanwu Hospital from February 2013 to November 2014, all of who were received EGFR-TKI as first-line treatment in the study." (PMID 28855035, 2017). "However, the clinical significance of plasma CEA level changes during different cycles of target therapy is unknown for lung adenocarcinoma patients with sensitizing EGFR mutations." (PMID 28705152, 2017). "Patients with lung adenocarcinoma diagnosed and undergoing a mutational analysis at the Karolinska University Hospital, Stockholm, Sweden between January 2009 and September 2015 were divided in three subgroups based on their mutational status (EGFR-, ALK-mutated, unexposed group)." (PMID 28560038, 2017). "However, it is unknown whether these TMs can be used as prognostic factors in patients with advanced lung adenocarcinoma and EGFR-sensitive mutations who are treated with EGFR TKIs." (PMID 29050327, 2017). "However, how EGFR mutation helps early lung adenocarcinoma invade local structures that has been rarely studied, and it is not known whether it can provide a basis for treatment in early lung adenocarcinoma." (PMID 28253871, 2017). "Thus, our findings could be useful non-invasive biomarkers to differentiate mutation status in EGFR gene in smoker lung adenocarcinoma male patients." (PMID 29383112, 2017). "We hypothesized that the AGER polymorphisms aggravate tumor-associated systemic inflammatory conditions, as indicated by elevated NLRs, and therefore AGER polymorphism could predict survival in patients with lung adenocarcinoma, independently of the effect of EGFR mutations." (PMID 29212235, 2017). "Patient #071, who was diagnosed with lung adenocarcinoma, stage IV due to metastases to the brain, adrenal gland, and bone (multiple spines, pelvic bone, humerus, femur, and ribs), had 125 variants including EGFR mutations (L858R and T790M) and multiple KRAS mutations." (PMID 29290998, 2017). "Thus, blocking autophagy may be a promising strategy to overcome resistance and increase sensitivity to afatinib in lung adenocarcinoma harboring activating EGFR mutations." (PMID 28676644, 2017). "In this series of patients with advanced lung adenocarcinoma and EGFR-sensitive mutations who were treated with EGFR TKIs, CEA could be used as a significant predictive and prognostic tumor marker when selected 10 ng/ml as cut off point of pretreatment serum CEA levels." (PMID 29050327, 2017). "Therefore, we suppose that PCI could bring survival benefit for patients with a high risk of BM during the course of EGFR-TKIs therapy from EGFR-mutated advanced lung adenocarcinoma." (PMID 27626317, 2016). "Therefore, we aimed to explore the potential imaging characteristics of the main tumor and intra-thoracic findings, as well as metastases and infiltration patterns, among patients with advanced-stage (stage IIIB–IV) lung adenocarcinoma and driver mutations in EGFR, KRAS, or ALK." (PMID 27518729, 2016). "However, the introduction of epidermal growth factor receptor (EGFR) tyrosine kinase inhibitors (TKI) for patients with advanced-stage lung adenocarcinoma harboring activating EGFR mutations has changed the clinical course and survival rates of the patients with this type of cancer dramatically." (PMID 26984681, 2016). "Moreover, development of personalized medicine of lung adenocarcinoma, the discovery of various genetic alterations that promote cancer growth and survival, such as EGFR mutations and EML4-ALK rearrangements, have revolutionized treatment paradigms for patients." (PMID 28018791, 2016).